ATF3 (activating transcription factor 3)
Diseases named in the same sentence as ATF3 in open-access papers (continued):
Sharing a sentence is not in itself a finding about the gene and the disease.
prostate carcinoma (continued). "ATF3 is involved in cell proliferation and survival, and is regulated by androgen in prostate cancer cells." (PMID 20021671, 2009). "In a prostate cancer model, ATF3 functions to promote metastasis." (PMID 38658567, 2024). "Interestingly, in human prostate cancer cells, the constitutively activated upstream promoter of the ATF3 gene leads to a higher expression of ATF3 in stress response, while expression from the downstream promoter is suppressed." (PMID 36769304, 2023). "However, our finding was not in accordance with a previous study, which indicated that ATF3 is induced by Wnt or the ectopic expression of β-catenin and Tcf in breast and prostate cancer cells." (PMID 34728784, 2021). "For example, upregulated ATF3 could be observed in prostate cancer by androgen stimulation and contributes to cell proliferation and cell cycle progression, suggesting the oncogenic role of ATF3." (PMID 34571936, 2021). "However, ATF3 also acts as a tumor suppressor in prostate cancer by blocking pro-survival pathways, such as androgen receptor and AKT pathways, ultimately leading to the inhibition of cell proliferation and invasion." (PMID 34571936, 2021). "ATF3 is induced by phosphatase and tensin homolog deleted on chromosome 10 (PTEN) loss in mouse prostate epithelium and then inhibits AKT activation, leading to reduction of the survival, proliferation, and invasiveness of prostate cancer cells." (PMID 32922364, 2020). "In summary, ATF3 may be upregulated by androgens, thus inducing prostate cancer cell proliferation and the G1-to-S-phase transition of the cell cycle." (PMID 32922364, 2020). "The stress response mediator, ATF3, was frequently down-regulated in prostate cancer." (PMID 31581661, 2019). "Several reports indicated that ATF3 expression is downregulated in a variety of human cancers, including colon cancer, liver cancer, multiple myeloma, neuroblastoma, bladder cancer, prostate cancer, malignant glioma and non-small cell lung carcinoma." (PMID 30376856, 2018). "In addition, ATF3 represses androgen-dependent genes by inhibiting androgen activity, resulting in prostate cancer development." (PMID 28860159, 2017). "ATF-3 is a key mediator of KLF6-induced apoptosis in prostate cancer cells." (PMID 28380462, 2017). "ATF3 protein levels were determined by immunoblot analysis, which showed that high levels of ATF3 were observed in normal human prostate tissue and LNCaP, androgen-dependent, prostate cancer cells." (PMID 23591848, 2013). "Also in favor of oncogenicity, the tumor suppressor gene Drg-1 mediates its anti-metastatic properties through ATF3 downregulation in prostate cancer." (PMID 24494067, 2013). "To determine the potential role of ATF3 SUMOylation on regulating the cellular proliferation of human prostate cancer cells, we first analyzed ATF3 expression in normal prostate tissues and prostate cancer cell lines." (PMID 23591848, 2013). "These collective data suggested that ATF3 overexpression plays an important role in promoting cell growth and colony formation of prostate cancer PC3 and DU145 cells by modulating CCND1/2 activity and SUMOylation is involved in and essential for this promotion." (PMID 23591848, 2013). "Prostate cancer up-regulation has been previously documented for ATF3, RUNX2 and ERG." (PMID 20021671, 2009). "Recent studies suggest that ATF3 (Activating Transcription Factor 3), a transcription factor responding to diverse cellular stresses and regulating oncogenic activities, acts as a tumor suppressor for the subset of prostate cancers harboring dysfunctional PTEN." (PMID 31366128, 2019).
prostate carcinoma (continued). "Similarly, KLF6 induces ATF3 overexpression promotes apoptosis in human prostate cancer cells." (PMID 31410216, 2019). "However, in prostate cancer and Hodgkin's lymphoma, ATF3 was found to be over-expressed and act as an oncogene, indicating that ATF3 may play differing roles in cancer development depending on the cell type." (PMID 25149542, 2014). "Therefore, ATF3 is a key mediator of KLF6-induced apoptosis in prostate cancer cells." (PMID 24222778, 2013). "In prostate cancer, both EZH2 and HDAC inhibitors collaboratively suppress the tumor suppressor function of ATF3." (PMID 40659662, 2025). "ATF3 is a downstream transcription factor of ROS, and increased levels of ATF3 can reduce the transcriptional level of FAK, reducing prostate cancer cells’ invasiveness." (PMID 36407100, 2022). "In fact, ATF3 promotes AKT activation and prostate cancer development in PTEN knockout mouse models." (PMID 31366128, 2019). "MYC, ATF3, PMEPA1, AURKB, and HMOX-1 were identified as novel targets of curcumin in both less aggressive and highly aggressive metastatic prostate cancer cells in our study." (PMID 31581661, 2019). "Taken together, our results demonstrate that SUMO modification of ATF3 influences CCND1/2 activity and cellular proliferation of prostate cancer PC3 and DU145 cells and explains at least in part how ATF3 functions to regulate cancer development." (PMID 23591848, 2013). "In the present study, we investigated the role of ATF3 SUMOylation on CCND activity and cellular proliferation in human prostate cancer cells." (PMID 23591848, 2013). "The higher (5 μM) dose of M344 in a panel of human derived cancer cell lines, MCF-7 (breast adenocarcinoma), PC3 (prostate carcinoma), SK-OV3 (ovarian carcinoma), and A549 (lung carcinoma) demonstrated consistent up-regulation of ATF3 protein expression." (PMID 20828393, 2010). "However, this analysis does not take into account the activity of HDACs, which are heterogenesously overexpressed in prostate cancer, and can also influence the expression of PRC2 targets, including ATF3, as shown throughout." (PMID 37104245, 2023). "Moreover, the depletion of ATF3 promoted activation of the AKT signaling, evidenced by higher extent of AKT phosphorylation, to accelerate prostate cancer development." (PMID 33794833, 2021). "Additionally, overexpression of ATF3 fosters the invasiveness and motility of human PC-3MM and ALVA prostate cancer cells." (PMID 32922364, 2020). "Notable genes in the predicted pathway included ATF3, JUNB, KLF6, NR4A2, ZFP36, DUSP5 and NEDD9, as well as STAT3 and IRF1 as novel upstream regulators, and SELE, CXCL1 and CXCL2 as novel downstream targets of NFκB in prostate cancer." (PMID 27078000, 2016). "Since CCND1/2 activity is required for cell cycle G1/S transition, we decided to determine whether ATF3 influences CCND1 expression, which further regulates cellular proliferation of human prostate cancer cells." (PMID 23591848, 2013). "Notably, ATF3 was recently reported to have been induced by the Wnt/β-catenin pathway and to play a role in the NDRG1-mediated suppression of metastasis of human breast and prostate cancer cells." (PMID 29966001, 2018). "All of these genes were down-regulated in patients who had disease that relapsed after a prostatectomy, which could be the result of negative feedback loops in lethal prostate cancer that turn off important cancer regulators, such as ZFP36, DUSP5, and ATF3." (PMID 27078000, 2016).
lung carcinoma (45 papers, 2010 to 2026). "On-treatment melanoma and residual disease lung cancer samples are also enriched for ATF3 and exhibit moderately increased expression of ISGs similar to wild-type DFFB persister and DTEP cells." (PMID 41249572, 2025). "In melanoma, breast, and lung cancer, ATF3 is correlated to an anti-tumour effect in fibroblasts through direct and indirect effects on cancer cells." (PMID 41198649, 2025). "In contrast, ATF3 acts as a tumor suppressor in lung cancer by inducing cancer cell apoptosis via activation of DR5." (PMID 40121894, 2025). "Herein, we developed the first multiplexed mouse model to study the impact of TBX2 subfamily loss, alongside associated signaling genes (Egr1, Chd2, Tnfaip3a, and Atf3) in Ras-driven lung cancer." (PMID 41705258, 2025). "When the serum from ATF3-transgenic mice was applied to breast and lung cancer cells, it was shown to enhance both breast and lung cancer cell proliferation." (PMID 38279150, 2024). "Similar to lung cancer, ATF3 functions as a tumor suppressor in colon and liver cancer by limiting cell proliferation and inducing apoptosis." (PMID 38586033, 2024). "The ATF3 protein, located in the cytoplasm and nucleus, promotes apoptosis and inhibits cisplatin-induced cytotoxicity in lung cancer A549 cells." (PMID 34142021, 2021). "We observed that DDIT3, pERK, and ATF3 mRNA levels were mainly upregulated upon 6-AN treatment in lung cancer cells." (PMID 34827081, 2021). "The oncogenic notion of ATF3 is further supported by the poorer survival of the lung cancer patients with higher level of ATF3, especially among the patients with lung adenocarcinoma." (PMID 35052581, 2021). "NDRG1’s overexpression reduces anticancer drug-induced cytotoxicity in lung cancer by downregulating the stress-inducible gene ATF3." (PMID 34142021, 2021). "For example, AK4 is a prognostic marker that facilitates metastasis in lung cancer via silencing ATF3, a transcription factor." (PMID 32549791, 2020). "Of note, a previous study found that AK4 promotes the metastasis of lung cancers by downregulating the transcription factor ATF3." (PMID 29866054, 2018). "Over-expression of ATF3 reduced the invasive potential of ovarian cancer cells, bladder cancer cells and lung cancer cells." (PMID 25149542, 2014). "ATF3 was discovered to be involved in cell invasion and metastasis of human ovarian cancer cells, lung cancer, and bladder cancer." (PMID 25149542, 2014). "In contrast, ATF-3 has been reported to play an important role in cisplatin-mediated apoptosis in lung cancer." (PMID 23533526, 2013). "High expression of ATF3 expression contributes to tumor malignancy in lung cancer." (PMID 37910161, 2023). "Although presented here data indirectly suggest that targeting ATF3 in DCs for inactivation may yield clinical benefits against lung cancer, two important considerations might complicate potential therapeutic approaches." (PMID 36333297, 2022). "However, in lung cancer, the upregulated ATF3 promotes cancer cell proliferation, invasion, and migration." (PMID 33816467, 2021). "For instance, miR-431-5p was found to be down-regulated in colon cancer and lung cancer, and circ_0001742 was reported to promote tongue squamous cell carcinoma by suppressing miR-431-5p, thus de-repressing activating transcription factor 3 (ATF3)." (PMID 34326275, 2021). "ATF3 is highly prominent in cancer that includes breast, laryngeal, and lung cancers." (PMID 34631548, 2021). "ATF3 expression mediates, in part, the cisplatin-modulated apoptosis in lung cancer." (PMID 32922364, 2020). "However, increased ATF3 expression was observed in lung cancer tissues/cells as compared with normal tissues/cells." (PMID 32922364, 2020). "In summary, AK4 stimulates metastasis of lung cancer by downregulation of ATF3 expression." (PMID 32922364, 2020). "Furthermore, AK4 is a marker of poor clinical outcomes that stimulates the metastasis of lung cancer by downregulation of ATF3 expression." (PMID 32922364, 2020).
lung carcinoma (continued). "Additionally, ATF3 knockdown has been proved to impair cellular growth and viability in Hodgkin lymphoma, glioblastoma, and lung cancer." (PMID 33050633, 2020). "AK4 promotes lung cancer malignant progression and recurrence at an ATF3-dependent manner." (PMID 32549791, 2020). "On the other hand, upregulation of ATF3 in lung cancer could promote cell proliferation, migration, and invasion." (PMID 30376856, 2018). "Nonetheless, other molecules implicated in this signaling pathway, such as ATF3 and MKP1, which has been related to both “de novo” and acquired resistance to cDDP in ovarian and lung cancer models should be considered in the final role of p38 MAPK in cDDP resistance." (PMID 22164285, 2011). "In lung cancer, intratumoral dendritic cells show reduced expression of cholesterol 25-hydroxylase (CH25H) due to activation of activating transcription factor-3 (ATF3) by tumor-derived factors." (PMID 40270603, 2025). "Butyrate can enhance ferroptosis induced by erastin in LC cells by upregulating ATF3 expression to reduce the expression level of SLC7A11, thereby inhibiting the growth of lung cancer cells." (PMID 39346734, 2024). "In this study, we found that AP2, ATF3, c-Myc, NF-YA, and SP1 are critical to USP22 mRNA expression in lung cancer cells." (PMID 36123698, 2022). "Our result revealed that ATF3 and ANKRD1 were downregulated in malignant cells and mice primary lung cancer tissues induced by PAHs." (PMID 34497759, 2021). "Because several genes, including DDIT3, TRIB3, and ATF3, were specifically increased due to verteporfin treatment in KRAS-mutant lung cancer cells, we focused on the ER stress pathway." (PMID 33830081, 2021). "In addition, ATF3 decreases nuclear factor kappa B subunit 2 (NFKB2) expression and reverses drug resistance in lung cancer cells." (PMID 36123698, 2022). "Moreover, we also observed that ANKRD1 and ATF3, as the target genes of EGR1, were significantly downregulated in malignant transformed cells and mice lung cancer tissues." (PMID 34497759, 2021). "Furthermore, IPA upstream analysis predicted the activation or inhibition state of many important transcription factors that were previously reported to be involved in the pathogenesis of lung cancer such as FOXM1, NRF2, TP63, NKX2-1, and ATF3 18,36–39." (PMID 31444368, 2019). "Butyrate can induce direct binding of ATF3 to the SLC7A11 promoter, thereby modulating the ATF3/SLC7A11 pathway, up-regulating ATF3 expression and decreasing SLC7A11 expression in lung cancer cells and activating erastin-induced iron death in lung cancer cells." (PMID 40520902, 2025). "Consistent with the function of ATF3 in suppressing CH25H expression, ATF3-null DCs exhibited a reduced OVA proteolysis, which was not increased after treatment with the lung cancer cell-conditioned media." (PMID 36333297, 2022).
colon carcinoma (41 papers, 2007 to 2025). "We utilized four machine learning algorithms to identify three key ferroptosis-related genes (TXNIP, SLC2A1, ATF3) that are closely associated with the development and prognosis of colon cancer from 52 differentially expressed genes." (PMID 38244591, 2024). "Down-regulation of ATF3 by ATF3-shRNA causes an increased tumor growth rate of HCT116 colon cancer cells as compared with control cells." (PMID 32922364, 2020). "This important result will be further addressed in future experiments, where loss of ATF3 function as well as ATF3-overexpression will be investigated in colon cancer cells with different genetic background." (PMID 21129190, 2010). "In addition, ATF3 is highly expressed in colon cancer cells, and its overexpression is associated with an increased invasive phenotype, further supporting its role in driving cancer progression and metastasis." (PMID 40754247, 2025). "ATF3 has been implicated in the progression of colon cancer, serving as a promoter in this process." (PMID 40754247, 2025). "Furthermore, this study is the first to demonstrate that loss of ATF3 via shRNA-mediated down-regulation increases the migration properties of HCT116 colon cancer cells in vitro and promotes tumor growth and metastasis in vivo." (PMID 21129190, 2010). "In contrast, we could show that in HCT116 colon cancer, loss of ATF3 function does result in a higher pro-migration capacity in vitro and an accelerated tumor growth with increased metastasis in vivo." (PMID 21129190, 2010). "It has been shown that the expression of PHGDH is regulated by many transcription factors, such as HOXA10, SMAD3 and ATF3, in endometrial endothelial cells, pulmonary epithelial cells and colon cancer cells." (PMID 39962071, 2025). "We have found that PXR confers resistance of liver and colon cancer cells to IR-induced DNA damage stress through stabilization of ATF3." (PMID 35372071, 2022). "In summary, in the current study, we find that PXR confers resistance of liver and colon cancer cells to IR-induced DNA damage stress through stabilization of ATF3, thus promoting ATF3-mediated ATM activation." (PMID 35372071, 2022). "In the current study, our data have disclosed that PXR protects liver and colon cancer cells from IR-induced DNA damage through ATF3-mediated ATM activation." (PMID 35372071, 2022). "In contrast, ATF3 was found to be down-regulated in esophageal squamous cell carcinomas, hepatocellular cancers, prostate and colon cancers and thus acts as a tumor suppressor." (PMID 33539340, 2021). "We found that both drugs led to an increase in ATF3 expression in human colon cancer cells and MEFs." (PMID 33370278, 2020). "The transcription factor NF-κB mediates anticancer agent-induced apoptosis in several types of cancer cell lines and mediates anticancer drug-induced ATF3 expression in colon cancer cells." (PMID 33082907, 2020). "First, we examined the effect of DACOR1 expression on ATF3 in two distinct patient-derived colon cancer cell lines, V852 and V866." (PMID 30348202, 2018). "Integration of these data sets with gene expression data sets, and functional studies of DACOR1 indicate a potential role of the ATF3 pathway in colon cancer." (PMID 30348202, 2018). "In a recent study, p38 was demonstrated to be activated by naringenin and to mediate the upregulation of ATF3 in human colon cancer cells." (PMID 28004841, 2016). "In line with the reported tumor suppressor role in colon cancer, ATF3 appeared to induce expression of genes involving in mitosis and stress responses while repressing genes regulating vasculature development, migration, and apoptosis." (PMID 27146783, 2016). "ATF3 has been demonstrated to be down-regulated in several types of tumors such as colon cancer and ovarian cancer." (PMID 25149542, 2014). "Another study reports that ATF2 can activate the expression of ATF3 in response to stress in colonic cancer cells." (PMID 25254641, 2014).